INSR (insulin receptor)
Diseases named in the same sentence as INSR in open-access papers (continued):
Sharing a sentence is not in itself a finding about the gene and the disease.
breast cancer (continued). "ErbB receptors can bind and phosphorylate insulin receptor substrates (IRS) and this may be critical for ErbB-mediated anti-estrogen resistance in breast cancer." (PMID 27765041, 2016). "In contrast to a small molecule inhibitor targeting IGF-1R and insulin receptor (IR), MK-0646 failed to improve anti-tumor response to hormonal therapy in ER-positive breast cancer xenografts." (PMID 27765027, 2016). "Furthermore, a high mRNA ratio of IGFBP-5/IGFBP-4 from patients’ tissue enhanced the power of its poor prognostic value, and also predicted resistance to the IGF-1R and INSR TKI, BMS-536924, in a breast cancer cell line." (PMID 26217584, 2015). "Since AZD5363 induces FoxO3a nuclear translocation in ER+/PIK3CA mutant breast cancer cells and ER mRNA in LTED cells, we examined whether knockdown of ER and/or FoxO3a affects AZD5363-induced transcription of IGF-IR, InsR, and IGF ligands." (PMID 23844554, 2013). "Besides, tyrosine kinases, namely the insulin receptor (IR) and insulin-like growth factor (IGF) receptors, are over-expressed in several human cancers, including cancer of the breast." (PMID 22554284, 2012). "Research has shown that the binding of insulin and IGF‐1 to the insulin receptor can activate the PI3K/AKT/mTORC signaling pathway, stimulating cell proliferation and the transcription of metabolic genes, which promotes the growth of cancer cells and prevents apoptosis in breast cancer cells." (PMID 40550558, 2025). "This led us to hypothesize a regulatory role for C/EBP-β, a predominant oncogenic transcription factor in breast cancer, modulated by several receptor tyrosine kinases, such as EGFR, fibroblast growth factor receptor (FGFR), insulin receptor (IR), and IGF-1 receptor (IGF-1R)." (PMID 38560690, 2024). "Even though our findings require validation in an independent cohort of ER+, IGF‐1R‐positive breast cancer patients on adjuvant tamoxifen, our data suggest that IGF‐1R/InsR inhibition might be an overlooked treatment option for patients with tumors harboring an activated IGF‐1R signaling route." (PMID 31490549, 2020). "Importantly, treatment with AZD9362 also enhanced the anti-tumor effects of the AKT inhibitor against MCF-7 xenografts, suggesting that combined inhibition of IGF-IR/InsR and AKT should be more effective than either agent alone in treating ER+ breast cancers that adapt to estrogen deprivation." (PMID 23844554, 2013). "Inhibition of the IGF-IR/InsR signaling pathway enhanced the action of AZD5363 against estrogen-deprived breast cancers, suggesting that combined treatment with an AKT inhibitor and a dual IGF-IR/InsR TKI merits evaluation as a potential treatment for endocrine-resistant breast cancer." (PMID 23844554, 2013). "Addition of an IGF-IR/InsR tyrosine kinase inhibitor (TKI) enhanced the action of AZD5363 against MCF-7 xenografts in ovariectomized mice devoid of estrogen supplementation, suggesting a novel and testable therapeutic combination for patients with ER+ breast cancer." (PMID 23844554, 2013). "Upregulation of IGF-IR/InsR and their ligands compensates for AKT inhibition in breast cancer cells with acquired resistance to estrogen deprivation, implying that AKT inhibitors may have limited clinical activity in endocrine-resistant breast cancers when used as single agents." (PMID 23844554, 2013). "However, in a subsequent manuscript from the same group, total insulin receptor protein levels were shown to be elevated in 2 of 3 breast cancer cell lines, but no quantitative difference in insulin receptor mRNA content was observed in these same cell lines." (PMID 22046260, 2011). "Therefore, alterations in the IR-A:IR-B transcript ratio observed in this study could significantly increase our understanding of the role of insulin receptor isoforms in breast cancer, independent of the total insulin receptor content in these tumors." (PMID 22046260, 2011).
breast cancer (continued). "Patients with ER+, IGF‐1R‐positive breast cancer without p‐IGF‐1R/InsR staining (n = 242) had tamoxifen benefit (HR 0.41, p = 0.0038), while the results for p‐IGF‐1R/InsR‐positive patients (n = 125) were not significant (HR 0.95, p = 0.3)." (PMID 31490549, 2020). "The positive correlation of DDR1 with IGF-IR and IGFBP2, but not with AKT, INSR or IGFBP5, was further confirmed in the TCGA breast cancer dataset." (PMID 26655502, 2016). "In the ER+ breast cancer cell lines, a specific antibody against IGF‐1R was not able to block downstream PI3K/MAPK signaling or tumor cell proliferation, unlike the dual IGF‐1R/InsR inhibitor linsitinib." (PMID 31490549, 2020).
Hypoglycemia (55 papers, 2008 to 2025). A decreased concentration of glucose in the blood. "Variants in the INSR gene should be considered as a differential diagnosis in patients presenting with postprandial hypoglycemia, even in adults." (PMID 39659391, 2024). "A hypoglycemia gene panel, using next-generation sequencing, identified a heterozygous nonsense variant in the INSR gene (NM_000208.4) c.3079C > T, p.(Arg1027*)." (PMID 39659391, 2024). "Most patients in the literature with a heterozygous pathogenic variant in INSR and fasting hypoglycemia developed persistent neonatal hypoglycemia shortly after birth." (PMID 39483531, 2024). "Genetic investigation with a hypoglycemia gene panel using next-generation sequencing identified a heterozygous INSR nonsense variant (NM_000208.4) c.3079C > T, p.(Arg1027*)." (PMID 39659391, 2024). "NICTH is a paraneoplastic syndrome that manifests through excess IGF‐2‐led insulin receptor activation, causing hypoglycaemia." (PMID 38411039, 2024). "Here we describe the case of a 10-year-old female with fasting and postprandial hypoglycemia who was found to have a missense variant in the INSR gene, which we functionally characterized." (PMID 39483531, 2024). "IAS must also be distinguished from hypoglycemia caused by insulin receptor antibodies, also known as type B insulin resistance." (PMID 36844104, 2023). "In fact, heterozygous mutations in INSR have been associated with familial hyperinsulinemic hypoglycemia, and a patient with recurrent hypoglycemia has been reported to have bilateral lower limb lipedema." (PMID 35207755, 2022). "Other potential but less common causes of hypoinsulinemic hypoglycemia include the production of autoantibodies against the insulin receptor and mutations in protein kinase B (PKB), also known as serine/threonine kinase AKT." (PMID 35282439, 2022). "Some tumors produce autoantibodies against insulin or the insulin receptor that cause hypoglycemia in the paraneoplastic setting." (PMID 35414906, 2022). "Only a few patients with a heterozygous INSR mutation associated with episodes of hypoglycaemia have been reported, mainly demonstrating post-prandial hypoglycaemia following oral glucose tolerance test." (PMID 31989990, 2020). "Several authors highlighted the occurrence of anti-insulin receptor AA, which binds to the insulin receptor, mimics insulin action, and causes fasting hypoglycemia." (PMID 32481667, 2020). "He presented with growth retardation, peculiar facial features, acanthosis nigricans, hypertrichosis, extremely high insulin levels, fasting hypoglycemia, and postprandial hyperglycemia, Whole-exome gene testing suggested compound heterozygous mutations in INSR (c.2246delG and c.2646 + 5G > A)." (PMID 36626508, 2022). "However type 1 IGF receptors disappear from the liver in adult life, which doesn’t explain the several reported cases of hypoglycaemia in adult life associated with heterozygous INSR mutations." (PMID 31989990, 2020). "Depending on the relative extents of these 2 effects, a variant in the INSR gene could possibly result in decreased insulin clearance, leading to increased levels of endogenous circulating insulin postprandially and thereby be causative of hypoglycemia." (PMID 39659391, 2024). "However, targeting the insulin receptor, as well as other receptors, may come with the risk of transient hypoglycemia and other unwanted side effects." (PMID 35203513, 2022). "This is evidenced by the finding that adult mice with central insulin receptor knockout show a reduced counterregulatory response to hypoglycemia compared to wild‐type mice." (PMID 39821966, 2025). "Isolated hypoglycemia in the presence of autoantibodies against INSR is exceptionally rare, and currently considered part of type B resistance syndrome." (PMID 40565151, 2025).
Hypoglycemia (continued). "This suggests that the variant results in constitutive and increased activation of the insulin receptor, which would result in both fasting and postprandial hypoglycemia and is consistent with the proband's phenotype." (PMID 39483531, 2024). "After the hypoglycemia episode, the patient suffered from hypokalemia, altogether indicating that the insulin receptor was involved." (PMID 37469410, 2023). "Taken together, the results shown in the present paper point to the paramount role of an adequate vitamin D signaling pathway in hypoglycemia induced by overactivation of the insulin receptor." (PMID 35406129, 2022). "There is potential use of insulin receptor antagonists as a therapeutic approach to control hypoglycemia in CHH." (PMID 32185602, 2020). "In contrast, insulin receptor mutants in humans (Donohue syndrome or the Rabson Mendenhall syndrome) are hyperinsulinemic and have fasting hypoglycemia." (PMID 30151194, 2018). "The patient developed autoantibodies that inhibited the binding of insulin to the erythrocyte's receptors and stimulated the insulin receptor leading to hypoglycemia." (PMID 26839722, 2015). "Recombinant growth hormone at supraphysiological doses increases IGFBP and ALS, thereby increasing ternary complex and preventing interaction with insulin receptor ultimately decreasing chances of hypoglycemia." (PMID 24194988, 2013). "The Zip14−/− phenotype included greater body fat, hypoglycemia and higher insulin levels, as well as increased liver glucose and greater phosphorylation of the insulin receptor and increased GLUT2, SREBP-1c and FASN expression." (PMID 23110240, 2012). "IGF-2 affinity for the insulin receptor (IR) can result in clinically significant hypoglycemia." (PMID 40270996, 2025). "Variants in INSR have been associated with a hypoketotic hypoglycemia phenotype, but the mechanisms by which variants in this gene cause hypoglycemia have not been clearly established." (PMID 39483531, 2024). "However, the GILT tagged GAA (reveglucosidase alfa) induced transient mild hypoglycemia in a few patients due to the IGF2 moiety that can bind the insulin receptor with low affinity." (PMID 35203513, 2022). "Hepatocellular damage may also lead to slow insulin receptor recycling, thereby aggravating malaria induced hypoglycaemia." (PMID 35923890, 2022). "Non-islet cell tumor hypoglycemia (NICTH) is a rare paraneoplastic syndrome that secretes incompletely processed high molecular weight insulin growth factor 2 (big-IGF2), which results in stimulation of the insulin receptor and subsequently induces hypoglycemia." (PMID 32393233, 2020). "There are several reports of autosomal dominant heterozygous INSR mutations causing hypoglycaemia in adults but to the best of our knowledge there is no data about heterozygous INSR mutations causing neonatal HH." (PMID 31989990, 2020). "Very rarely, INSR autoantibodies bind to and stimulate the INSR resulting in hypoglycemia." (PMID 24533136, 2014). "Furthermore, insulin coordinating inhibition of insulin signaling through MFGE8 provides a physiological feedback mechanism to prevent the possibility of persistent and/or excessive activation of insulin receptor signaling which can lead to life-threatening hypoglycemia." (PMID 38199575, 2024). "Our last specific question related to the risks (e.g. tumours, hypoglycemia, cardiac hypertrophy, other soft tissue overgrowth) and benefits (assessed by A1c) of recombinant human IGF-1 (rhIGF-1) or IGF-1/IGFBP3 composite in patients with pathogenic INSR variants." (PMID 37794082, 2023). "A high-molecular-weight form of insulin-like growth factor-2 (IGF-2), known as “big” IGF-2, is occasionally produced in various tumor types regardless of whether the origin is mesenchymal or epithelial, and can lead to hypoglycemia through insulin receptor (IR) signaling." (PMID 32993631, 2020).
Hypoglycemia (continued). "However, if GAD037, as an INSR activator, is to be further developed as a neurogenic or neuroprotective agent, it is crucial to evaluate whether it may induce adverse effects such as hypoglycemia." (PMID 40227445, 2025). "In conclusion, we present a heterozygous missense variant in the INSR gene (c.1151A>G, p.Asn384Ser) that results in constitutive and increased activation of the human insulin receptor, leading to both fasting and postprandial hypoglycemia without evidence of increased insulin secretion." (PMID 39483531, 2024). "However, insulin receptor mutations known in humans including the Donohue syndrome or the Rabson Mendenhall syndrome are non-obese and have post-prandial hyperglycemia but fasting hypoglycemia." (PMID 30151194, 2018). "Also, in response to recurrent hypoglycemia, GhIRKO mice exhibited nearly identical blood glucose and plasma CRR hormone levels as littermates with intact insulin receptor expression (floxed-IR mice), despite higher plasma ghrelin in GhIRKO mice." (PMID 37334290, 2023). "Of further note, the affinity of proinsulin and PPI for the insulin receptor is much lower than that of insulin itself, thus minimizing undesirable metabolic side effects upon systemic absorption, e.g. hypoglycemia, which we did not observe." (PMID 34447366, 2021). "Nevertheless, serum glucose levels do not always correspond with intracellular hypoglycemia, and this with ketogenesis, as serum glucose levels might not reflect insulin receptor functions, metabolic stress, or ensuing starvation leading to catabolic metabolism." (PMID 35682159, 2022). "Non-islet cell hypoglycemia (NICH) is hypoglycemia due to the overproduction of insulin-like growth factor-2 (IGF-2) and its precursors which can activate the insulin receptor." (PMID 31156561, 2019). "The precise mechanism of hypoglycemia in SRS and likewise IGF2 dysfunction is not clear to date, but several factors are discussed: IGF2 presumably is able to bind to both IGF1 and IGF2 receptors as well as the insulin receptor and interacts with IGFBP3, possibly influencing glucose homeostasis." (PMID 33922271, 2021).
metabolic syndrome (55 papers, 2011 to 2025). A cluster of metabolic risk factors for CARDIOVASCULAR DISEASES and TYPE 2 DIABETES MELLITUS. "The sweet taste receptors are associated with G protein α-gustducin, and GPCR crosstalk with several receptors, and particularly, the insulin receptor (IR) has been implicated in the development of metabolic syndrome." (PMID 30884834, 2019). "Insulin signaling via the insulin receptor (IR) may be associated with the amelioration of diet-induced metabolic syndrome." (PMID 36570152, 2022). "Increased triglycerides, as a risk factor for metabolic syndrome in the Stressed syndrome prototype, might induce brain insulin receptor resistance to further reflect a) enhanced secretion of triglyceride lipoproteins and b) impaired clearance of these lipoproteins." (PMID 33670473, 2021). "This would be consistent with animal models, where inactivation of the insulin receptor in the hypothalamus has been shown to result in systemic IR, dyslipidemia, and depressive-like behavior." (PMID 39233885, 2024). "Most women with PCOS have insulin resistance from perturbed insulin receptor signaling, altered adipokine secretion, and abnormal steroid metabolism, which collectively promote glucose intolerance, dyslipidemia, and metabolic syndrome with increased adiposity." (PMID 39345868, 2024). "Moreover, InsR plays a key role in the pathophysiology of metabolic syndrome (MetS), which increases the risk of developing type 2 diabetes (T2D), cardiovascular disease (CVD), hypertension, and dyslipidemia." (PMID 32252239, 2020). "Wetherefore used the expression levels of the proteins identified by thehierarchical cluster algorithm to investigate the insulin receptor signalingpathway in the metabolic syndrome patients." (PMID 22442648, 2011). "Our result consisted with previous studies stated that fermented red ginseng prevents metabolic disturbance and dyslipidemia via improving insulin receptor substrate and glucose transport type 4 in rats, red ginseng has been also proved to promote an insulin-like acid peptide in diabetic condition." (PMID 31231500, 2019). "It is not clear at present whether the preserved or increased plasma adiponectin seen in insulin receptor dysfunction may play a role in the protection from fatty liver and dyslipidemia in that state." (PMID 27766312, 2016). "In a study that examined the effects of neonatal overfeeding on InsR in the hypothalamus, the researchers observed an increase in methylation of the CpG island of the insulin receptor promoter in over-nourished rats, resulting in rapid weight gain and the development of metabolic syndrome." (PMID 41040868, 2025). "Thus, our findings regarding INSR upregulation in tumors from Black women could link a more aggressive tumor phenotype to the metabolic syndrome commonly diagnosed in Black patients." (PMID 39622796, 2024). "The cumulative impact of impaired HPA regulation combined with compromised glucocorticoid and insulin receptor activity, aggravated by inflammatory cytokines, might explain the high rate of metabolic syndrome, diabetes, dyslipidemia, and osteoporosis in the bipolar population." (PMID 25202283, 2014). "Conversely, permanent abrogation of INSR expression in adipocytes (AIRKO) resulted in severe lipodystrophy, with metabolic abnormalities such as IR, altered glucose homeostasis, dyslipidemia and fatty liver disease, leading to decreased lifespan." (PMID 30754657, 2019). "Collectively, these studies provide strong evidence that there exists an interaction between GPCRs and the insulin receptor, which may provide insight into the implications of NNS consumption on the development of metabolic syndrome." (PMID 30884834, 2019). "Supporting this hypothesis, pathway analysis using KEGG predicted socs inhibition of insulin receptor activation and gene set enrichment analysis (GSEA) predicted enrichment (normalized enrichment value of − 3.93) of a network describing metabolic syndrome." (PMID 32994480, 2020).
metabolic syndrome (continued). "Finally, we aim to expand on several pathologies that are either classified as or are exacerbated by metabolic syndrome and identify additional disease states on which GPCR-biased agonism for the insulin receptor may play a role." (PMID 29462993, 2018).